LGALS9 (galectin 9)
Diseases named in the same sentence as LGALS9 in open-access papers (continued):
Sharing a sentence is not in itself a finding about the gene and the disease.
cancer (continued). "After the analysis of fold changes, upregulation in the mRNA level of LGALS1, LGALS3, LGALS4, LGALS8, and LGALS9 was detected in cancer patients compared to normal ovarian tissue." (PMID 36050693, 2022). "T-cell immunoglobulin and mucin domain-3 (TIM-3) is an activation-induced inhibitory receptor and binds to its ligand galectin-9 (Gal-9) to induce immune tolerance and T-cell exhaustion in cancer." (PMID 36558902, 2022). "Both exosomal Tim-3 and galectin-9 expression have been found to be positively correlated with clinicopathological features, including patient age, tumor size, distant metastasis, and cancer stage." (PMID 35158999, 2022). "CD276 showed the highest positive correlations with JMJD8 in 15 cancers, followed by LGALS9, VSIR, and TNFRSF4." (PMID 35898493, 2022). "Major ligands for TIM3 include galectin-9 (Gal-9), and Ceacam-1, which are expressed on macrophages and some cancers, and CD4 T cells, respectively." (PMID 34868044, 2021). "CD47 is only one of many immune checkpoints overexpressed on the surface of cancer cells; others include Galectin-9 and programmed cell death ligand 1 (PD-L1)." (PMID 33540720, 2021). "The expression of galectin-3 and galectin-9 on PC-3 cells that are proteins binding to β-galactoside sugars to provide potential biomarkers and therapeutic targets in particular cancer should be checked in the future." (PMID 33807287, 2021). "Cancer cells expressing TLR4 release TGF-β in response to stimulation with HMGB1 followed by TGF-β-induced upregulation of galectin-9 expression, forming such an HMBG1-triggered autocrine loop." (PMID 34234778, 2021). "TGF-β displays both autocrine and paracrine activities and, through the transcription factor Smad3, induces expression of galectin-9, an immunosuppressive protein which impairs the anti-cancer activities of natural killer and cytotoxic T cells." (PMID 34234778, 2021). "The role of galectin-9 in the process of carcinogenesis is being investigated, due to its assumed ability in cancer cell apoptosis, its role in metastatic spread of many cancers and as a prediction marker of poor outcome." (PMID 33799622, 2021). "For example, a meta-analysis demonstrated that overexpression of LGALS9 in cancer tissues was related to a longer cancer-specific survival (CSS) and OS in cancer patients." (PMID 33854625, 2021). "Many other targets of miR-455-5p have been reported, such as galectin-9 and PIK3R1 and these interactions have been implicated in cancer development." (PMID 33962657, 2021). "Gal-9 expression is significantly altered in most human cancers; in all the cancer types with altered Gal-9 expression, the Gal-9 gene (Lgals9) is overexpressed." (PMID 33547304, 2021). "Specifically, TIM-3, through the interaction with its ligand, galectin-9, downregulates the population and activity of T helper 1 (Th1) cells and promotes the “exhaustion” of T cells in many types of cancer." (PMID 31952209, 2020). "Galectin-9 plays a crucial role in determining the ability of cancer cells to escape host immune surveillance." (PMID 33295886, 2020). "We next assessed the possibility of detecting induced vesicle damage in cancer cell spheroids established from HeLa or MCF7 cells expressing YFP–galectin-9." (PMID 32286269, 2020). "Galectin-9 is one of the crucial proteins used by various types of cancer cells to suppress cytotoxic immune responses and thus, escape immune surveillance." (PMID 33295886, 2020). "Galectin-9 has been evaluated histologically and as a prognostic marker for several cancer types, including gastric cancer, non-small cell lung cancer, hepatocellular carcinoma, melanoma, and breast cancer." (PMID 32486344, 2020). "The expression of Tim-3 and galectin-9 protein in cancer tissues were higher than in normal cervix tissues." (PMID 32699524, 2020). "Human cancer cells express significantly higher levels of galectin-9 compared to healthy human cells." (PMID 33295886, 2020).
cancer (continued). "Cell surface-based or secreted galectin-9 can impair anti-cancer activities of NK and cytotoxic T cells." (PMID 33295886, 2020). "Tim-3 acts as a receptor and possible trafficker for galectin-9 and also participates in the transduction of moderate growth signals from galectin-9 into cancer cells (for example AML cells) as well as pro-apoptotic signals into cytotoxic T cells." (PMID 33295886, 2020). "Galectin-9 is one of the key proteins employed by a variety of human malignancies to suppress anti-cancer activities of cytotoxic lymphoid cells and thus escape immune surveillance." (PMID 33295886, 2020). "This pathway can be recommended for targeting in order to design novel anti-cancer immunotherapeutic approaches based on inhibiting the Tim3-galectin-9 pathobiochemical pathway thus enabling the immune system to attack and eradicate malignant tumors." (PMID 31354733, 2019). "Within this family, Galectin-9 (Gal-9) has gained attention as a regulator of cell adhesion and polarity, induction of cancer cell death, and regulator of both adaptive and innate immunity." (PMID 31430907, 2019). "The Tim-3-galectin-9 secretory pathway is known to protect various types of cancer cells against host immune surveillance." (PMID 31024310, 2019). "We next examined T cell exhaustion using 2 markers (PD-1 and T cell Ig and mucin domain 3 [TIM-3]) in CD8+ T cells, whose ligands (PD-L1 and LGALS9) are known to be expressed in some cancer cells from solid tumors." (PMID 31483286, 2019). "Secreted galectin-9 contributes to anti-cancer immune suppression by killing cytotoxic T lymphocytes and impairing the activity of natural killer (NK) cells, thus allowing for disease progression." (PMID 31354733, 2019). "Our findings demonstrate the activity of the Tim-3-galectin-9 biochemical pathway in breast and various other types of human cancer cells and its possible implication in suppression of host anti-cancer immune surveillance." (PMID 31354733, 2019). "The effects of galectin-9 on cancer cells seem to be paradoxical, as some studies have reported that galectin-9 promotes cell proliferation in many blood cancers, while other studies have reported that galectin-9 induces cell apoptosis in cancers." (PMID 29316949, 2018). "This review focuses on the biological effects of galectin-1, galectin-3 and galectin-9 in various cancers and discusses anticancer therapies that target these molecules." (PMID 29389859, 2018). "In this review, malignant cell apoptosis and galectin-9 are reviewed and the potential for galectin-9 to be an anti-cancer agent is presented." (PMID 28045432, 2017). "Expression of TIM-3 and its ligand galectin-9 has been described on several immune cells and galectin-9 can also be overexpressed by cancer cells." (PMID 29163783, 2017). "Galectin-9 has potential as an anti-cancer agent, but these questions should be resolved before drawing major clinical conclusions." (PMID 28045432, 2017). "Administering galectin-9 to induce cellular apoptosis is a well-accepted approach in cancer therapy; however, the opportunity to apply this concept for antiviral therapy remains to be investigated." (PMID 28991189, 2017). "Treatment of cancer cells with Galectin-9 alone is sufficient to restrict metastatic seeding." (PMID 41996163, 2026). "Currently, LGALS9 has emerged as a promising new target for cancer immunotherapy." (PMID 40362421, 2025). "TIM-3 has multiple ligands, among them, galectin-9 is gaining relevance in cancer." (PMID 38697976, 2024). "Overexpression of LGALS9 has been reported in distinct cancer types, and targeting LGALS9 may restore antitumour immunity." (PMID 39422697, 2024). "CD45 targeted by LGALS9 has been demonstrated by animal experiments to have a role in promoting cell stemness and resistance to radiotherapy in cancer cells, and a related study revealed that up-regulated expression of CD45 promotes cancer cell survival in mice." (PMID 39583114, 2024).
cancer (continued). "So far, there have been no reports regarding associations between cancer and LGALS9 polymorphisms, despite galectin-9 being documented as playing an important role in cancer pathology." (PMID 36768365, 2023). "An in vitro study demonstrated that galectin-9 could activate neutrophils to enact a killing effect on cancer cells, and neutrophils also contribute to the secretion of galectin-9." (PMID 37371482, 2023). "Furthermore, treatment with galectin-9 induces apoptosis in human cancer and immunocompetent cells, such as T lymphocytes." (PMID 37047155, 2023). "The results might provide further insight into the role of galectin-9 inhibition in cancer treatments." (PMID 37371482, 2023). "In contrast, galectin-9 tends to evoke an anti-inflammatory response, rendering it a promising intervention in the treatment of autoimmune and inflammatory conditions such as intracerebral hemorrhage, cancer, allograft rejection, and chronic asthma." (PMID 38067100, 2023). "Thus, the structure and diversity of galectin-9 should be elucidated in future studies to determine how it is involved in cancer and apoptosis." (PMID 37047155, 2023). "The development of novel therapies targeting cancer immune mechanisms, including galectin-9, may be necessary." (PMID 37047155, 2023). "Furthermore, the administration of extracellular galectin-9 induces apoptosis of human cancer and immunodeficient cells." (PMID 37047155, 2023). "A limited number of studies have shown an association between TIM-3 polymorphisms and cancer risk in the Asian population; however, there is no study on the role of LGALS9 polymorphisms in cancer." (PMID 36768365, 2023). "Inhibiting galectin-9 may help to activate adaptive immunity during cancer treatment, regarding the ICIs PD-1/PD-L1." (PMID 37371482, 2023). "Interestingly, we have recently reported that the TGF-β-Smad3 pathway is involved in regulating galectin-9 expression in human cancer and embryonic cells." (PMID 35223897, 2022). "Antitumor immunity could be enhanced by TIM-3 antibodies, since T helper 1 (TH1) cell responses could be inhibited by TIM-3, the ligand of which is galectin 9 (which itself enjoys an upregulation in several cancer types, such as breast cancer)." (PMID 35145371, 2022). "TIM3 is expressed on immune cells, while galectin-9 is expressed on cancer cells." (PMID 35242139, 2022). "Based on transcriptome analysis and ligand-receptor interactions, we found that CCR5-CCL5, LGALS9-PTPRK could also take part in the OGC-cancer cell interaction." (PMID 36148946, 2022). "The pathway of TIM3 and galectin-9 has been known for their role in cancer malignancies." (PMID 35242139, 2022). "Galectin-9 is a positive prognosis biomarker for patients with some types of cancer." (PMID 34572756, 2021). "In terms of immunosuppression in cancer, galectin-9 (Gal-9) is the most important TIM-3 ligand." (PMID 33801964, 2021). "TGF-β induces production of the immunosuppressive protein galectin-9 in cancer cells." (PMID 34234778, 2021). "We hypothesised that HMGB1 could upregulate galectin-9 expression in cancer cells through the activation of TGF-β production induced in a TLR4-dependent manner." (PMID 34234778, 2021). "Altered expression of the LGALS9 gene has been reported for several cancer types." (PMID 32902187, 2020). "Epigenetic alterations play important roles in gene expression and may participate in the altered expression of LGALS9 reported in cancer." (PMID 32902187, 2020). "In some cancers, galectin-9 is related with a good prognosis." (PMID 32063906, 2020). "We hypothesised that TGF-β, a growth factor with autocrine activity, is responsible for the upregulation of galectin-9 expression in cancer cells." (PMID 33295886, 2020).
cancer (continued). "Cancer-associated exosomes not only shuttle immune regulatory molecules such as PD-L1, TRAIL, TGF-β, IL-10, FasL, galectin-9, HSP72, and PGE2 to exert an immunosuppressive effect, but they also to trigger the Fas/FasL pathway and induce apoptosis in CD8+ T cells." (PMID 32121073, 2020). "This study suggests that targeting galectin-9 or preventing its interaction with TIM-3 could potentially act as a novel immunotherapy approach to enhance NK cell functions against cancer." (PMID 32063906, 2020). "Both Tim-3 and galectin-9 act to suppress anti-cancer immune surveillance." (PMID 31354733, 2019). "We hypothesized that the Tim-3-galectin-9 pathway may be involved in the immune escape of cancer cells of different origins." (PMID 31354733, 2019). "Furthermore, we found that human cell lines originating from a wide range of different cancers express detectable amounts of both Tim-3 and galectin-9 proteins." (PMID 31354733, 2019). "Galectin-9 is a widely expressed protein that is involved in immune regulation and tumorpathogenesis and serves as a marker of a poor prognosis in various types of cancers." (PMID 27028892, 2016). "Moreover, LGALS9 expression correlates with poor prognosis in multiple human cancers." (PMID 41271007, 2025). "Additionally, resistance to PD-1/PD-L1 ICIs may also be influenced by molecules that modulate PD-1 signaling to promote immune escape, such as galectin-9 (Gal-9), implicating such proteins as putative targets for cancer immunotherapy." (PMID 39339217, 2024). "Since conventional systemic chemotherapy has limited therapeutic efficiency against PDAC, understanding the cancer immune microenvironment, including galectin-9 in PDAC, and exploring its potential as a new therapeutic strategy may improve the prognosis of this deadly disease." (PMID 37047155, 2023). "By halting the TIM-3/galectin-9 interaction in leukemic cells, sabatolimab has therefore the potential to limit this autocrine feedback loop, and may have a direct impact on leukemic cells, limiting their self-renewal and reducing cancer growth." (PMID 36196369, 2022). "Finally, it is important to note that galectin-9 interventions in cancer may take some considerations on kinetics and receptor expressions into account." (PMID 34572756, 2021). "Importantly, targeted defunctionalization of mitochondria in malignant cells may be a novel strategy for anti-cancer immunotherapy since it reduces cell surface presence of galectin-9 capable of suppressing anti-cancer activity of cytotoxic lymphoid cells." (PMID 31024310, 2019). "Furthermore, one of recombinant-type human galectin-9, hG9NC (null), which has greater protease-resistant properties than endogenous original molecules, has demonstrated anti-cancer activity, inducing apoptosis on epithelial cancer species and hematological malignancies." (PMID 28045432, 2017). "High-dimensional cytometry confirmed discrete, cancer-enriched myeloid clusters expressing CD47, SIRPα, PD-L1, CD73, and Galectin-9." (PMID 41683933, 2026). "LEC-derived immune-inhibitory ligands dampen effector T cell function in cancer, neuroinflammation, and infection, and we confirmed the expression of 2 exemplar molecular candidates, PVR and LGALS9, at both the transcript and protein level." (PMID 40663403, 2025). "Altogether, this suggests galectin-9 as potential target for immunotherapy in CLL and likely other cancer entities." (PMID 40775219, 2025). "Galectin-9 expression also correlates with worse survival in CLL and other cancers, suggesting its role in immune evasion and potential as a therapeutic target." (PMID 40775219, 2025). "HPV-positive CC tumors exhibited epithelial cells with significant enrichment of immune checkpoint ligands (LGALS9, CD274, and TNFRSF14), whereas HPV-negative carcinomas predominantly activated the CD80/86-CTLA4 pathway." (PMID 41035636, 2025).
cancer (continued). "Our analysis revealed that elevated PLEK2 expression was significantly associated with increased expression of several key immune checkpoint molecules, such as CD276 (B7-H3), CD274 (PD-L1), LGALS9, PVR (CD155), and FAS across a wide spectrum of cancers." (PMID 39546161, 2024). "Similar to the potential cross-talk between mesothelial cells and cancer cells, we identified possible interactions between LA-TAMs/mesothelial cells by SPP1, RETN, LGALS9, NAMPT, and HBEGF secretion." (PMID 37649596, 2023). "In the context of cancer, the interaction between Galectin-9 and PD-1, as well as TIM3, plays a crucial role in regulating T-cell apoptosis, making it a promising target for cancer immunotherapy." (PMID 37666809, 2023). "In various cancers, TIM3 and Galectin-9 (Gal9) interact to suppress both innate and adaptive immunity." (PMID 37666809, 2023). "Other immune checkpoint ligands, such as NECTIN2, LGALS3, LGALS9, and SELPLG, were highly expressed in cancer cells or other infiltrating immune/stromal cells." (PMID 36529697, 2023). "While the expression level of LGALS9 was high mostly in TAMs, and also cancer cells and ductal cells, P4HB was found to be widely expressed by cancer cells, ductal cells and TAMs, respectively in our SC datasets." (PMID 37945567, 2023). "Studies show that immune checkpoints TDO2, PDCD1, LGALS9, and PVR play an important role in cancer treatment and prognosis." (PMID 36686663, 2022). "Galectin-9 expression in these cells was upregulated by TGF-β, as in other cancer cells studied in the past, and this correlated with TGF-β-induced Smad3 phosphorylation." (PMID 35223897, 2022). "Three proteins have not previously been associated with FTC, but are related to thyroid function or other types of cancer, namely, major vault protein (MVP), GEM‐interacting protein (GMIP) and galectin‐9 (LGALS9)." (PMID 35194950, 2022). "Results from our scRNA-seq analyses identified several potential interactions involving the cancer stem cell marker CD44 with ligands secreted by CAFs such as HGF, HBEGF, FGF2 and LGALS9." (PMID 36273171, 2022). "We also assessed the correlation between BMI1 expression and immune checkpoint-related molecules, including PD-L1, Galectin 9, HVEM, and IDO1, all of which are important marker genes for cancer immune therapy." (PMID 36199791, 2022). "On the other hand, the immune suppression molecule galectin-9 (Gal9) was primarily expressed on CD4+CD25+ Tregs in OS, with significantly higher frequencies than in non-cancer controls, as well as higher than other solid tumors." (PMID 35433427, 2022). "Cancer cells can express regulatory ligands such as PD-L1, CD80/CD86, or Galectin-9 to provide a negative regulatory signal to T lymphocytes expressing their respective receptors PD-1, CTLA-4, and TIM-3, resulting in T cell exhaustion." (PMID 35159351, 2022). "CD48, CD200 and VISTA are also downregulated in cancer samples, while CD276, LGALS9 and PVR are upregulated in cancer tissue." (PMID 33806327, 2021). "In TLR4-positive cancer cells, HMGB1 triggers the formation of an autocrine loop which induces galectin-9 expression." (PMID 34234778, 2021). "Cancer-associated exosomes not only shuttle immune regulatory molecules such as FasL, TGF-β, galectin-9, and HSP72, which help cancer cells escape the immune system, but also trigger the Fas/FasL pathway to induce CD8+ T cells toward the apoptotic pathway." (PMID 32121073, 2020). "Cancer cells investigated in our study—GBM43 and U87MG—express TIM-3 ligands, including galectin-9 and CEACAM-1, with both dominating in percentage on GBM43 cells and in MFI on U87MG cells." (PMID 32858904, 2020). "Its ligand, Galectin-9 (Gal-9) is expressed on cancer cells, and the complex formed by the checkpoint TIM-3 and its ligand Gal-9 induces apoptosis of Th1 cells, and, consequently, a reduction in CD8+ T cells whose proliferation depends on Th1-secreted IL-2." (PMID 32310956, 2020).